FGF2 (fibroblast growth factor 2)
Diseases named in the same sentence as FGF2 in open-access papers (continued):
Sharing a sentence is not in itself a finding about the gene and the disease.
breast carcinoma (continued). "In summary, our study has demonstrated that FGFR1 amplification in ER + breast cancer cells activate a collateral JAK-STAT pathway and leads to p21 upregulation, which inhibits the proliferation of cancer cells and enhances their stemness properties with FGF2 simulation." (PMID 38553760, 2024). "To test if the role of FGF2 could shift from promoting proliferation to inducing a stem-like state in FGFR1 amplified cells, we next investigated the effect of FGF2 on cancer stemness-like traits using FACS analysis for ALDH and CD44 (two known markers of breast cancer stemness)." (PMID 38553760, 2024). "TNBC patients with breast cancer typically exhibit higher levels of FGF2 than non-TNBC patients." (PMID 40135140, 2024). "Finally, we assessed acquisition of stem-like ALDHhiCD44+ phenotype in breast cancer cells treated with BM, tnLCM or tbLCM in the presence or absence of a neutralizing monoclonal FGF2 antibody." (PMID 38581619, 2024). "Importantly, we previously developed a monomeric FGF2-based conjugate that exhibited high toxicity against FGFR1-overproducing cancer cells in vitro and showed efficient tumor growth retardation in an FGFR-positive human breast cancer xenograft model in mice." (PMID 37373291, 2023). "Furthermore, the results suggest that all these markers should be used in the earlier stages of the disease, since an analysis of BRCA patients indicated that the FGF2, FGFBP1, TGFA, TGFBR3, and IGF1R gene expression levels were present in late stages 3 and 4 of breast cancer." (PMID 36430763, 2022). "Furthermore, FGF2 secreted by CAFs stimulated cell migration and invasiveness in a breast cancer cell line (MDA-MB-231), which could be inhibited by an FGF2-neutralizing antibody." (PMID 34830951, 2021). "CAFs are also responsible for the secretion of fibroblast growth factor-2 (FGF-2), an essential signaling molecule responsible for angiogenesis, and expresses stromal-derived factor-1 (SDF-1) which induces metastasis in breast cancer by acting as a chemotactic factor for circulating ECs." (PMID 34122412, 2021). "The inhibition of angiogenesis in xenografted human breast cancer (MDA-MB-231) by formononetin was found to modulate FGF2-induced micro-vessel growth that suppressed the emergence of rat aortic rings and angiogenesis through the repression of FGF2-initiated activation of FGFR2 and AKT signaling." (PMID 31052435, 2019). "Similarly, in a syngeneic rat model of breast cancer, overexpression of FGF2 failed to produce any metastases." (PMID 26793421, 2016). "Since we have reported that the PI3K-dependent activation of PLCγ1 is a key event in migration of breast cancer cells and PLCγ1 is necessary for breast cancer migration and invasion, we investigated whether this novel PI3K/PLCγ1 pathway was involved in the FGF-2-dependent migration of HUVEC." (PMID 20011604, 2009). "We also showed that loss of DACH1 inhibited metastatic outgrowth in the lung suggesting that FGF2 and other soluble factors secreted in the microenvironmental may play a critical role in regulating DACH1 expression and orchestrate metastatic behavior of breast cancer cells." (PMID 38581619, 2024). "It is of interest that FGF-2 isoforms did not protect a breast cancer cell line (MCF-7) from Dox toxicity, suggesting the possibility, in need of further investigation, that an FGF-2-based therapy may not affect the toxicity of anthracyclines against at least some types of cancer cells." (PMID 29152091, 2017). "The research shows that BGF1 can significantly inhibit the proliferation of HUVECs, 4T1 breast cancer cells, U87 glioblastoma cells, and SKOV3 ovarian cancer cells induced by FGF2, while the linear structure of BGF2 has no such effect." (PMID 41155018, 2025).
breast carcinoma (continued). "By comparing three-dimensional spheroid growth of ER + breast cancer cells with and without FGFR1 amplification, our research discovered that FGF2 treatment can paradoxically decrease proliferation in cells with FGFR1 amplification or overexpression." (PMID 38553760, 2024). "In breast cancer cells with FGFR1 amplification (CAMA1 and MDA-MB-134), FGF2 elevated non-canonical FGFR downstream signaling pathways, especially JAK-STAT pathway, to promote p21 expression and modulate the ratio of p21/CCND1 to drive cell cycle arrest." (PMID 38553760, 2024). "The entire mechanism involving FGF2, PBX1/PBX2, and HOXB7/HOXB8 in breast cancer tumorigenesis is not clear." (PMID 37445737, 2023). "FGF2, but not FGF1, was shown to enhance cisplatin toxicity in MCF-7 breast cancer cells and A2780 ovarian cancer cells, but not in SKOV3 ovarian cancer cells or a panel of pancreatic cancer cell lines." (PMID 34830951, 2021). "In the present study, we have determined that the expression levels of FGF2 and S100A4 are higher in TNBC with respect to non-TNBC patients when analyzing “The Invasive Breast Cancer Cohort of The Cancer Genome Atlas” (TCGA) dataset." (PMID 33946884, 2021). "In nontransformed cells, 18 kDa FGF-2 is often found, whereas the 23 kDa FGF2 is more often present inside of transformed cells, including breast cancer cells (MCF-7)." (PMID 32230722, 2020). "However, there are reports showing that FGF2/FGFR2 protein level in glioma and breast cancer tissue does not differ from that in non-malignant parental cells, or is even lower." (PMID 34830951, 2021). "However, AXL silencing did not have any effect on the FGF2, VEGF-A, FGFR1, VEGFR1, and VEGFR2 expression of MDA-MB-231 breast cancer cells (data not shown), suggesting that AXL-mediated VM formation may be independent of the VEGF/VEGFR and FGF/FGFR axis." (PMID 33374832, 2020).
melanoma (174 papers, 2000 to 2026). A malignant, usually aggressive tumor composed of atypical, neoplastic melanocytes. "Overexpression of FGF‐2 is associated with increased cell proliferation in various cancers, including lung, breast, gastric, prostate, and melanoma." (PMID 40079158, 2025). "Another study has shown that the expression of FGF2 by human melanoma cells mediated the promotion of tumor-associated B cells to express IGF1." (PMID 34830951, 2021). "In VGP primary melanomas, co-expression of FGF2 and FGFR1 is significantly associated with increased density of microvessels." (PMID 31167513, 2019). "Rather, we observed that FGF2, whose expression significantly increased in melanoma-associated fibroblasts upon A2BR stimulation, directly promotes the proliferation of B16.F10 melanoma cells." (PMID 27590504, 2016). "Administration of A2BR agonist Bay60-6583 enhances the expression of CXCL12 and FGF2 in melanoma-associated fibroblasts in an A2BR-dependent manner." (PMID 27590504, 2016). "Melanoma-associated fibroblasts grown on polylysine-coated plates and treated with 10 nM Bay60-6583 for 24 hours showed increased expression of both FGF2 and CXCL12 compared to vehicle-treated cells (Ctr)." (PMID 27590504, 2016). "In human melanoma produced as a subcutaneous tumor model in nude mice, introducing an episomal vector encoding antisense FGF2 or FGFR1 cDNA could entirely prevent the formation of tumors by blocking angiogenesis." (PMID 37108717, 2023). "We performed pharmacodynamic studies on patients with KIT-mutated melanoma treated with nilotinib, which suggested that the FGF2 axis may be a mechanism of resistance in this subset of melanoma." (PMID 32344828, 2020). "FGF2 has been previously implicated as a melanoma growth factor and immunosuppressive agent." (PMID 30824801, 2019). "During angiogenesis in melanoma, FGF-2 cooperates with heparinase, which enzymatically cleaves the glycosaminoglycan chains of heparan sulfate proteoglycans, which act as a receptor or coreceptor for FGFR." (PMID 39866233, 2025). "The same study identified FGF-2, a cytokine actively produced by melanoma cells capable to control the differentiation of normal human keratinocytes, as one of the major soluble factors responsible for this phenomenon." (PMID 40869222, 2025). "Regarding melanoma progression, FGF-2 modulates melanoma migration capacity through a syndecan 4-dependent mechanism." (PMID 39334952, 2024). "FGF2 is a key regulator of melanoma angiogenesis and metastasis, and FGF2-induced melanoma angiogenesis is a heparan sulfate glycosaminoglycan chain that can be degraded by heparanase (HPSE) or HPSE (HS) regulation." (PMID 38393692, 2024). "There was also upregulation of Matrin-3, a downstream component of the FGF2 pathway that mediates melanoma cell proliferation and survival, and BUB3, a mitotic checkpoint regulator." (PMID 39272836, 2024). "As one of the proangiogenic factors in CAFs, FGF2 is a promising target for normalizing vessel tubes in lung cancer, breast cancer, melanoma and pituitary tumors." (PMID 39075612, 2024). "A strong association between the number of microvessels, tumor cells positive for FGF-2, mast cell count, and tumor growth has been established in human melanoma." (PMID 38791873, 2024). "FGF2 plays an important role in melanoma progression and antibodies blocking FGF2 have been proposed as a therapy in metastatic melanoma." (PMID 36614248, 2023). "Consistently, the FGF genes FGF1 and FGF2 are highly expressed in CAF cells in the melanoma tissue from female patients." (PMID 35134150, 2022). "FGF2 is essential for the migration of M5 melanoma cells by downregulating FAK Tyr397 phosphorylation during fibronectin-mediated cell adhesion and, thereby promoting cell migration." (PMID 34282767, 2021).
melanoma (continued). "PTX3 has been seen to prevent epithelial-mesenchymal changes induced by FGF-2 in human and mouse melanoma cells andalso to prevent metastatic potential by inhibiting FGF-2-mediated cell proliferation and angiogenesis." (PMID 34048179, 2021). "In a study using VEGFR2-Fc-resistant murine melanoma models, the FGF2 signaling pathway was found to play a key role between endothelial cells and pericytes in maintaining tumor vasculature in acquired anti-VEGF-resistant tumors." (PMID 33807778, 2021). "Expression of FGF2 in melanoma is most likely due to a combination of autocrine secretion by tumoral cells and paracrine secretion by stromal cells from the tumor microenvironment." (PMID 32344828, 2020). "Another study also validated that increased expression of THBS1 is associated with an invasive and metastatic phenotype of melanoma, as part of a Slug-independent motility program that includes the melanoma-related VEGF/VEGFR-1 and FGF-2 pathways." (PMID 32894090, 2020). "Altogether, the mechanism of YB-1 release from melanoma cells shows similarities to the process of FGF2 secretion, which is ATP-dependent and involves its recruitment to the plasma membrane." (PMID 32824741, 2020). "We showed that although KIT inhibition markedly decreased cell viability in melanoma cell lines with distinct KIT mutations, this effect was lessened in the presence of FGF2 due to inhibition of BIM expression by MAPK pathway activation." (PMID 32344828, 2020). "We performed a pharmacodynamic study during a phase II clinical trial with nilotinib in KIT-altered melanoma, and showed that the expression of growth factors, such as FGF2, was significantly high at baseline and reduced during nilotinib therapy in responders." (PMID 32344828, 2020). "Melanoma secretes fibroblast growth factor 2 (FGF2), which actives B cells through its binding to fibroblast growth factor receptor 3 (FGFR-3) and promotes the release of insulin-like growth factor 1 (IGF-1)." (PMID 33036192, 2020). "The increase of CD44 after FGF2 treatment enhanced the directed migration of several cell types, including periodontal ligament cells, endothelial cells, and melanoma cells." (PMID 31191685, 2019). "More recent studies have shown that the majority of melanoma cell lines concomitantly overexpressed FGF2, FGF5, and FGF18 and diverse isoforms of FGFRs." (PMID 31167513, 2019). "In 2/3 of melanomas, FGF2 was also expressed by keratinocytes in the epidermis, and FGFR1 was commonly detected in the epidermis." (PMID 31167513, 2019). "Regarding melanoma cells, it has been demonstrated that they produce basic fibroblast growth factor (FGF2) which triggers the production of the tumor-supportive insulin-like growth factor 1 (IGF-1) by B cells present in the tumor niche." (PMID 31086070, 2019). "Melanoma cells have been reported to constitutively express fibroblast growth factor 2 (FGF2), which is an autocrine factor and promotes the proliferation, angiogenesis, and metastasis of melanoma cells." (PMID 31035725, 2019). "It was demonstrated that wild-type melanoma cell lines were more responsive to FGF2 than BRAF mutant or NRAS mutant cell lines." (PMID 31167513, 2019). "In line with this interpretation, excessive angiogenesis, a hallmark of melanoma, and the progression from a radial growth phase to a vertical growth phase has been shown to require high angiogenic activity dependent on FGF1, FGF2 and VEGFA." (PMID 29666124, 2018). "Mechanistically, it was described that FGF2 drives melanoma cell migration through a syndecan-4 and focal adhesion kinase-dependent mechanism." (PMID 29235576, 2017). "Taken together, the UPR regulates FGF1 and FGF2 expression in human melanoma and reduction of the UPR using a chemical chaperone reduces cell viability and invasion." (PMID 29235576, 2017). "Human melanoma cells constitutively produce the growth factor FGF-2, which activates tumor-infiltrating B cells to produce the growth factor IGF-1." (PMID 28928360, 2017).
melanoma (continued). "Overexpression of FGFs was reported, for instance, for FGF8 and FGF19 in hepatocellular carcinoma (HCC) and for FGF2 in multiple cancers including melanoma and mesothelioma." (PMID 29152117, 2017). "Taken together, these results indicate that FGF2 released from fibroblasts upon A2BR stimulation induces melanoma cells proliferation, as reported by other authors." (PMID 27590504, 2016). "We determined that A2BR stimulation induces the expression of FGF2 and CXCL12 in melanoma-associated fibroblasts." (PMID 27590504, 2016). "FGF2 produced by Bay60-6583-treated fibroblasts directly enhanced the proliferation of melanoma cells." (PMID 27590504, 2016). "In summary, this study shows that A2BR activation in tumor-associated fibroblasts triggers the expression of microenvironmental tumor-promoting factors in a murine model of melanoma, including FGF2 and CXCL12." (PMID 27590504, 2016). "Among them we found the miR-222-based upregulation of VEGF and FGF2 well known to play major roles in melanoma cell growth and tumor angiogenesis according to autocrine and paracrine functions." (PMID 26912358, 2016). "Together, our data reveal an important role for A2BR in stimulating FGF2 and CXCL12 expression in melanoma-associated fibroblasts." (PMID 27590504, 2016). "Treatment of melanoma-associated fibroblasts with the A2BR agonist Bay60-6583 enhanced CXCL12 and FGF2 expression." (PMID 27590504, 2016). "FGF2-dependent B16-F10 melanoma cells represent a prototypic model of experimental metastasis following their injection in the bloodstream of mice or zebrafish embryos." (PMID 25609197, 2015). "We also observed that IL-6 and VEGF-A are able to enhance the expression of β3-AR in melanoma cells, while β2-AR is upregulated by IL-8, FGF-2 and VEGF-A, thereby suggesting a feed-forward loop between NE and its cognate receptors β3/β2-ARs." (PMID 25474135, 2015). "In melanoma, FGF2 upregulation was found to be accompanied by the expression of FGFRs that triggers an autocrine loop of activation required for melanoma growth and survival." (PMID 25609197, 2015). "FGF2 promotes melanoma cell migration via down-regulation of focal adhesion kinase (FAK) and subsequent loss of cellular adhesion." (PMID 25763355, 2015). "Relevant to this point, CDV also inhibits the in vivo growth of murine B16 melanoma cells, a FGF2-dependent tumor cell line [26 and references therein]." (PMID 25609197, 2015). "Antisense-mediated inhibition of FGF2 or FGFR1 led to growth regression of xenografts formed by human melanoma cells." (PMID 26056081, 2015). "FGF-2 treatment of melanoma cells resulted in the reduction in syndecan-4 expression and downregulation of FAK Y397-phosphorylation thus decreasing cell attachment on FN and promoting their migration." (PMID 23844358, 2013). "FGFR inhibition is highly relevant to melanoma, where autocrine stimulation via FGF2/FGFR1 constitutes a pivotal role in proliferation and survival." (PMID 21494657, 2011). "Antisense targeting of FGF-2 in melanoma cells completely blocked tumor growth and inhibited tumor angiogenesis in vivo." (PMID 24281035, 2010). "Moreover, melanoma cells co-expressing α2bβ3 and αvβ3 integrins were shown to also have an increased expression of FGF-2." (PMID 39866233, 2025). "Moreover, activated CAFs release hepatocyte growth factor (HGF), vascular endothelial growth factor (VEGF), and fibroblast growth factor 2 (FGF2), which promote angiogenesis and activate survival pathways in melanoma cells." (PMID 40649909, 2025). "FGF-2 may be induced by the activity of matrix metalloproteinases (MMPs) released by melanoma cells, and a significant correlation between the percentage of FGF-expressing tumor cells, the number of mast cells, and melanoma progression has been evidenced." (PMID 38791873, 2024).